OSTF1 (osteoclast stimulating factor 1)
Description:
Induces bone resorption, acting probably through a signaling cascade which results in the secretion of factor(s) enhancing osteoclast formation and activity.
Synonyms: SH3P2; OSF; bA235O14.1
Tractability: Antibody: its Gene Ontology location is reachable by antibodies, with high confidence. PROTAC: ubiquitination databases record sites on it; its protein half-life has been measured.
Gene: Protein-coding gene on chromosome 9 (75,088,480 to 75,149,429, forward strand). Ensembl gene ENSG00000134996.
Subcellular location: Cytoplasm
Subcellular location (Human Protein Atlas): Cytosol
Pathways (Reactome):
Immune System: Neutrophil degranulation
Gene Ontology:
Molecular function: protein binding; SH3 domain binding
Biological process: ossification; signal transduction
Cellular component: cytosol; extracellular region; ficolin-1-rich granule lumen; secretory granule lumen; cytoplasm
Genetic constraint (gnomAD): Loss-of-function variants: 3 observed, 1.65 expected, observed/expected ratio (o/e) 1.82, 90% interval 0.62 to 1.94. That is too few expected variants to judge how well the gene tolerates losing a copy. Missense variants: 16 observed, 13.42 expected, observed/expected ratio (o/e) 1.19, 90% interval 0.8 to 1.76. Synonymous variants: 8 observed, 5.59 expected, observed/expected ratio (o/e) 1.43, 90% interval 0.8 to 1.92.
Homologues: Orthologues: chimpanzee OSTF1 (100% identical), macaque OSTF1 (99% identical), dog OSTF1 (98% identical), mouse Ostf1 (96% identical), guinea pig OSTF1 (95% identical), rat Ostf1 (92% identical), pig OSTF1 (88% identical), zebrafish ostf1 (81% identical), tropical clawed frog ostf1 (78% identical), Caenorhabditis elegans Y106G6H.14 (49% identical), Drosophila melanogaster CG44838 (29% identical), Drosophila melanogaster ckn (28% identical).
Diseases named in the same sentence as OSTF1 in open-access papers:
OSTF1 is named in the same sentence as 9 diseases in open-access papers, as found by Europe PMC text mining. Sharing a sentence is not in itself a finding about the gene and the disease. The quoted sentences say what the papers report.
osteopetrosis (3 papers, 2012 to 2023). Osteopetrosis, also known as marble bone disease, is a descriptive term that refers to a group of rare, heritable disorders of the skeleton characterized by increased bone density on radiographs. "We concluded that loss of OSTF1 confers mild osteopetrosis-like phenotype caused by an increase in trabecular number but not thickness." (PMID 28936620, 2017).
asthma (1 paper, 2022). "Based on the available diagnosis information, we assigned the 42 asthma cases into comorbidity subgroups; only subgroups 5 and 3 involving three genes (OSTF1, COX10, and FAM129B) contained five or more individuals, and were included in these analyses." (PMID 36344522, 2022). "OSTF1 expression was significantly reduced while COX10 was overexpressed in asthmatics in subgroup 5 “Musculoskeletal”, compared to the expression levels in the non-asthma controls or in the asthma cases not in subgroup 5." (PMID 36344522, 2022).
spinal muscular atrophy (1 paper, 2017). A motor neuron disease that affect the muscles, and characterized by muscle weakness and atrophy resulting from progressive degeneration and irreversible loss of the anterior horn cells in the spinal cord (i.e., lower motor neurons) and the brain stem nuclei. "OSTF1 has also been demonstrated to interact with Survival of Motor Neuron 1 and 2 (SMN1 and SMN2 respectively), the loss of which leads to spinal muscular atrophy." (PMID 28936620, 2017). "OSTF1 has been reported to interact with SMN, a spinal muscular atrophy gene." (PMID 28936620, 2017).
OSTF1 also shares sentences with these, for which no sentence is quoted: infection (2 papers); ovarian carcinoma (2); bacterial infection (1); blast (1); lymphoma (1); renal carcinoma (1).